AIPL1 (AIP like 1 HSP90 co-chaperone)
Diseases named in the same sentence as AIPL1 in open-access papers (continued):
Sharing a sentence is not in itself a finding about the gene and the disease.
visual disorders (1 paper, 2024). "Overall, a better understanding of the mechanism of PDE6 maturation and the roles of AIPL1 and Pγ will help to design therapeutic strategies to treat visual disorders linked to mutations in the AIPL1, PDE6G, and PDE6H genes." (PMID 38110033, 2024).
retinopathy (9 papers, 2013 to 2025). "These genes also affect the timing of sleep, for example, mutations in human CRX and AIPL1 were shown to cause inherited retinopathy and the associated symptoms of severe sleep abnormalities or insomnia." (PMID 40101169, 2025). "There were disagreements about the association of AIPL1 PRD mutations with retinopathies." (PMID 41465493, 2025). "It is worth mentioning that the presented table provides a large number of monoallelic heterozygous cases that are considered to be associated with LCA or another retinopathy, while only one AIPL1 variant, p.Ala352_Pro355del, is shown to cause autosomal dominant CORD and jPR." (PMID 41465493, 2025). "The animal model based gene therapy trials for other LCA genes like LCA1 (GUCY2D), LCA4 (AIPL1) and LCA6 (RPGRIP1) are also in progress, which further provides a prospect for the effective treatment regime in inherited blinding retinal disorders." (PMID 24066033, 2013). "However, it remains to be determined whether AIPL1 is required only for PDE6, and whether retinopathies in LCA4 are due solely to PDE6 dysfunction." (PMID 28378769, 2017).
cancer (1 paper, 2025). A tumor composed of atypical neoplastic, often pleomorphic cells that invade other tissues. "According to the meta-analysis of the cancer dataset, a down-regulation in the expression of AIPL1 in different tumours was observed." (PMID 41465493, 2025). "However, in more detailed published data of this author, the fold change in AIPL1 expression between normal and cancer tissues did not exceed 1.5 in any of the considered datasets." (PMID 41465493, 2025).
AIPL1 also shares sentences with these, for which no sentence is quoted: congenital blindness (2 papers); Bardet-Biedl syndrome (1); cataract (1); Cerebellar atrophy (1); choroideremia (1); dominant cone-rod dystrophy (1); infection (1); Jalili syndrome (1); late-onset retinal degeneration (1); night blindness (1); Nystagmus (1); pyelonephritis (1); recessive retinitis pigmentosa (1); renal failure (1); tumor (1); X-linked disease (1); X-linked juvenile retinoschisis (1).